TNF (tumor necrosis factor)
Diseases named in the same sentence as TNF in open-access papers (continued):
Sharing a sentence is not in itself a finding about the gene and the disease.
endometriosis (continued). "We delve into the specific shared risk loci, such as TRIM32 and SLC44A4, and demonstrate how they converge on dysregulated biological pathways, notably IL-1, TNF-α, and MAPK/ERK signaling that drive both peripheral inflammation in endometriosis and neuroinflammation in migraine." (PMID 42222530, 2026). "Epidemiological data on young women treated with anti-TNFα therapy and endometriosis incidence have not been published." (PMID 40508002, 2025). "Clinical observations also indicate that inflammatory mediators, such as cyclooxygenase-2 (COX-2), interleukin-1 beta (IL-1β), interleukin-8 (IL-8), tumor necrosis factor alpha (TNF-α), and prostaglandin E2 (PGE2), are significantly elevated in the peritoneal fluid of patients with endometriosis." (PMID 40004233, 2025). "Additionally, our human study demonstrated increased EZH2 expression in endometriotic lesions, accompanied by upregulation of ERβ and TNFα, as well as suppression of ERα, indicating that EZH2 plays a significant role in endometriosis development." (PMID 40630095, 2025). "In the secondary analyses, the endometriosis cases with pain with bowel movements had lower levels of TNF-α (GM: 7.18; 95% CI: 6.66–7.73) compared to those without pain with bowel movements (GM: 8.06; 95% CI: 7.41–8.77; p = 0.05) when measured using Ella." (PMID 40508188, 2025). "Additionally, peritoneal macrophages in women with endometriosis exhibit an overexpression of both ERα and ERβ, along with elevated levels of inflammatory cytokines, including VEGF, IL-6, and TNF-α." (PMID 38612685, 2024). "In women without endometriosis, endometrial cells do not implant in ectopic locations because normal apoptotic mechanisms are activated by TNF-α through the TNFR1 receptor." (PMID 38785987, 2024). "Thus, we were able to show that the expression of the M1 macrophage marker genes TNF and IL12B was significantly decreased in the endometriosis foci, and the expression of the M2 macrophage marker gene ARG1 was significantly increased." (PMID 39253270, 2024). "Bedaiwy and colleagues demonstrated that measuring serum IL-6 alongside peritoneal TNF-α accurately distinguishes between women with and without endometriosis." (PMID 39767772, 2024). "It has been theorized that increased release of inflammatory cytokines (e.g., prostaglandins, interleukins (IL), tumor necrosis factor (TNF-α) from stromal, epithelial, smooth, or immune cells) contributes to the initiation, development and progression of endometriosis." (PMID 38540637, 2024). "Even though TNF-α is a physiological cytokine in the proliferative and secretory-phase endometrium, scientific data indicate a correlation between the concentration of TNF-α in peritoneal fluid and the stage of endometriosis." (PMID 39458478, 2024). "A meta-analysis of these studies was not feasible because each study reported different positive threshold values (TNF-α levels showing a significant difference between patients with and without endometriosis)." (PMID 39767772, 2024). "They found elevated levels of pro-inflammatory markers, including TNF-α, IL-6, and IL-1β, in the control group rather than in those with endometriosis." (PMID 39767772, 2024). "Furthermore, TNF-α by inducing PGE2 in stromal cells of eutopic tissue, promotes the progression of endometriosis." (PMID 38868448, 2023). "For instance, higher levels of pro-inflammatory cytokines, such as interleukin (IL)-1, 6, 8, and 10, tumor necrosis factor (TNF)-alpha, and vascular endothelial growth factor (VEGF), have been detected in the peritoneal fluid of infertile women with endometriosis." (PMID 37240662, 2023). "Several studies have demonstrated higher concentration of TNF-α in the peritoneal fluid of women with endometriosis than those without, as well as a direct correlation between TNF-α level and disease severity." (PMID 37143676, 2023). "The authors claim that TNF-α level can be a good predictor of endometriosis in non-invasive methods." (PMID 37630196, 2023).
endometriosis (continued). "They suggested that there is still not enough evidence to support TNF-α treatment for pelvic pain in patients with endometriosis." (PMID 37630196, 2023). "Moreover, TNFα and IL-1β activate the NK-κB signaling pathway, which in turn controls the expression of cytokines and chemokines such as IL-1, IL-6, IL-8, TNF-α, as well as ICAM-1 able to boost inflammation and COX-2 expression in endometriosis implants." (PMID 37447296, 2023). "NF-κB pathway activity leads to increased levels of pro-inflammatory cytokines, including interleukin (IL)-1β, IL-6, IL-8, tumor necrosis factor (TNF)-α, and interferon (IFN)-γ, in the peritoneal fluid, serum, and follicular fluid (FF) of women with endometriosis." (PMID 37020589, 2023). "Notably, inhibition of miR-138 expression promotes inflammation by increasing levels of TNF-α, IL-1β, IL-6, and IL-18 through activation of the NF-κB signaling pathway and VEGF in endometriosis." (PMID 37834449, 2023). "In addition, inflammatory cytokines such as TNF-α and IL-6 activate c-jun terminal kinases (JNK) in the endometrial cells of endometriosis patients." (PMID 37033937, 2023). "A study pointed out that endometriosis patients can be differentiated from those without by measuring their relative serum IL-6 and PF TNF-α levels." (PMID 35592328, 2022). "The transcriptional activity of several proinflammatory cytokines/chemokines, such as IL1, IL6, IL8, TNF-α, RANTES, MIF, and ICAM1, is activated by NF-κB signaling, indicating the key role of NF-κB in the inflammatory responses in endometriosis 11, 13, 14, 18, 19, 21-27." (PMID 35864971, 2022). "In an endometriosis rat model, the angiotensin II receptor blocker losartan reduced TGF-β, and the surface area of endometriosis lesions was decreased as were the plasma levels of the angiogenic factors and inflammatory markers VEGF, TNF-α, PTX-3, and CRP." (PMID 35628346, 2022). "Interleukin (IL)-6 and tumor necrosis factor (TNF)-α are cytokines that are detectable at a higher level in the peritoneal fluid of women with endometriosis than in that without endometriosis." (PMID 36359553, 2022). "We found that the TNF signalling pathway, the IL-17 signalling pathway, and the MAPK signalling pathway were significantly enriched in the eutopic endometria of women with endometriosis." (PMID 34539624, 2021). "In conclusion, stimulation with IL-2 increased the percentages of CD107a + CD56+ cells among PMBCs from women with endometriosis but did not increase the levels of the cytokines produced by these cells, TNF-α and IFN-γ." (PMID 34616540, 2021). "There is an abundance of inflammatory molecules, including glycodelin, ROS, TNFα, NGF and PGE2 in the peritoneal fluid of women with endometriosis, which may contribute to the induction of a more pro-nociceptive state." (PMID 33132854, 2020). "Genistein could regulate estrogen receptor-α and estrogen receptor-β, and reduce the TNF-α, IL-6, VEGF, and HIF-1α levels in ectopic lesions in the endometriosis murine model." (PMID 32210799, 2020). "Despite its ineffectiveness in suppressing TNF-α levels, oral octyl gallate induction was able to reduce COX-2 levels, another inflammation mediator that plays an important role in the progression of endometriosis." (PMID 32685413, 2020). "In addition, FC inhibited inflammation by regulating the levels of VEGF IL-1β and TNF-α and suppressed EMT in endometriosis mice." (PMID 33266505, 2020). "In a surgically transplanted endometriosis mouse model, macrophage secretion of the angiogenic factors VEGF, TNFα and macrophage inflammatory proteins (MIP-1α and MIP-2) into the peritoneal fluid in early stages of endometriosis progression correlated with a peak in active angiogenesis in lesions." (PMID 33132854, 2020). "TNFα expression is increased in peritoneal fluid of women with endometriosis, and its levels correlate with disease severity, while a negative correlation has been identified between TNFα and reproductive outcomes." (PMID 32325785, 2020).
endometriosis (continued). "IL-37 synthesis is enhanced by IL-1β, TNF-α, IFN-γ, and TGF-β in endometriosis." (PMID 32145751, 2020). "Specifically, increased endometrial TNF, IL-1β, and CCL17 expression are observed in endometriosis." (PMID 36304708, 2020). "Genes having Pgene < 0.1 for both endometriosis and migraine (Pbinomial-test = 1.85 ×10−°3) were significantly enriched for biological pathways, including interleukin-1 receptor binding, focal adhesion-PI3K-Akt-mTOR-signaling, MAPK and TNF-α signalling." (PMID 32121467, 2020). "Similarly, IL-1β, IL-6, TNF-α, and prostaglandin E2 (PGE2) were found to be rich in the peritoneal fluid of women with endometriosis." (PMID 31636643, 2019). "TNF-α promotes the production of prostaglandins PGF2 and PGE2 by epithelial and stromal endometrial cells in endometriotic lesions and stromal cells from eutopic endometrium of women with endometriosis by inducing COX2 overexpression through NF-κB activation." (PMID 32063886, 2019). "In the early development stage of endometriosis, acute inflammatory responses and tissue breakdown were induced by pro-inflammatory cytokines such as interleukin (IL)-6, IL-1β, interferon (IFN)-γ, and tumor necrosis factor (TNF)." (PMID 31636643, 2019). "Xiaozheng decoction also could relieve dysmenorrhea and pelvic pain and improve qi stagnation and blood removal in endometriosis patients, which may be related to lower levels of CA125, CA199, MMP-3, MMP-9, VEGF, and TNF-α in serum." (PMID 30402122, 2018). "Anti-inflammatory drugs including tumor necrosis factor (TNF)-α inhibitors, peroxisome proliferator-activated receptor-g (PPAR-g) agonists, and antibody against matrix metalloproteinases (anti-MMP) exert therapeutic effects on endometriosis." (PMID 29871974, 2018). "Along the same lines, work using an estrogen receptor beta (ERβ)-overexpressing syngeneic mouse model of endometriosis suggests that non-genomic effects of ERβ play a role in the TNFα-mediated dysregulation of endometriosis progression." (PMID 30087267, 2018). "TNF-α, a pro-inflammatory cytokine, was one of the early non-hormonal targets for potential endometriosis therapy." (PMID 26949527, 2016). "The TNF-α level is increased in the PF of women with endometriosis, but clinical trials of anti-TNF-α therapies did not alleviate pain symptoms." (PMID 27294113, 2016). "A significantly increased secretion of TNF-α and IL-6 in the culture media of peritoneal macrophages of endometriosis patients was found in response to E2 compared to nontreated macrophages." (PMID 26198055, 2015). "Endometriosis-related CCC is thought to be a chronic inflammatory disease, characterized by increased production of pro-inflammatory cytokines such as IL-1, IL-6, IL-8, IL-10, and TNF-α." (PMID 25366985, 2014). "Furthermore, TNFα, various interleukins, and HGF, which are known to be significantly elevated in the peritoneal fluid of women with endometriosis, also contribute to proliferation of endometriotic cells." (PMID 24927773, 2014). "It has been reported that neutralization of TNF activity with recombinant human TNFRSF1A (r-hTBP1) was as effective as GnRH antagonist in inhibiting the development of endometriosis without hypoestrogenic effects in baboons." (PMID 25165691, 2014). "NF-κB-activated macrophages express proinflammatory, growth, and angiogenic factors, such as inducible Nitric Oxide (iNOS), cyclooxygenase-2 (COX-2), IL-1, IL-6, IL-8, TNF-α, and vascular endothelial growth factor (VEGF), which contribute to endometriosis pathogenesis and possible carcinogenesis." (PMID 24039864, 2013). "Patients diagnosed with endometriosis demonstrated significantly heightened levels of inflammatory cytokines, specifically interleukin-1 beta (IL-1β), interleukin-6 (IL-6), interleukin-8 (IL-8), vascular endothelial growth factor, CCL2, CCL5, and tumor necrosis factor-alpha (TNF-α)." (PMID 40303639, 2025).
endometriosis (continued). "In addition, increased levels of specific Th1 cytokines, tumor necrosis factor (TNF)-α, and IL-2 have been found in women suffering this disease, with a high presence in cases of deep infiltrating endometriosis, again linking this inflammatory pattern to the severity of the condition." (PMID 38999290, 2024). "High levels of malondialdehyde (MDA), pro-inflammatory cytokines (IL-6, TNF-α, and IL-1β), angiogenic factors (IL-8 and VEGF), monocyte chemoattractant protein-1 (MCP-1), and oxidized LDL (ox-LDL) were detected in the peritoneal fluid of endometriosis patients." (PMID 36835217, 2023). "In addition to these two biomarkers, there are also a number of proteins related to tissue inflammation, including IL-1, IL-6, IL-8, TNF-alpha, ICAM-1, MMPs, TIMPs, or VEGF, that may prove useful for endometriosis detection." (PMID 35453583, 2022). "Endometriotic cells treated with TNF‐α activate peritoneal macrophages via pro‐inflammatory cytokines such as IL‐6 and MCP‐1, which has a vital role in initiating, progressing, and protecting endometriosis through the promotion of invasion and proliferation of endometriotic cells." (PMID 36310658, 2022). "Therefore, the synergism of TNFα-induced apoptosis and IFN-mediated necroptosis might have a critical role in the prevention of endometriosis progression by effectively removing endometrial debris." (PMID 36358904, 2022). "In addition, we also evaluated the production of TNF-α in C107a + CD56+ cells in the PBMC from women with endometriosis and women without endometriosis." (PMID 34616540, 2021). "However, the administration of the TNF antagonist, imfliximab, in women with endometriosis did not reduce the pain symptoms or the size of the lesions." (PMID 34945174, 2021). "A recent study sequenced RNA from eutopic endometrial macrophages from women with endometriosis which exhibited a significantly greater (z-score ≥ 2.00) pro-inflammatory phenotype (activation of NF-kB pathways and increased upstream TNF regulators) not observed in controls." (PMID 36304032, 2021). "Our results revealed that HMGB-1 was upregulated in ectopic endometrium, which was also positively correlated with inflammatory cytokines IL-6, TNF-α, and IL-1β, as well as autophagy-related protein beclin-1, suggesting that HMGB-1 might be involved in endometriosis." (PMID 33815277, 2021). "Tumor necrosis factor-alpha (TNF-α), interleukin one beta (IL-1β), and interleukin six (IL-6) are all elevated as well as the angiogenic factors (VGEF), the growth factors, and adhesion molecules all of which play a positive role in the occurrence, maintenance, and progression of endometriosis." (PMID 33354460, 2020). "Endometriosis is considered an inflammatory disease, due to increased levels of activated macrophages and cytokines such as interleukins (IL-6, IL-8, IIL-1β), tumor necrosis factor-alpha (TNF-α), and macrophage migration inhibitory factor (MIF), in the peritoneal fluid of affected women." (PMID 32143439, 2020). "The crosstalk between oocytes and sperms may is blocked during fertilization by these inflammation activities due to progesterone resistance and reduced sperm affinity to the zona pellucida through TNF, IL-1, migration inhibitory factor, oxidative stress, and the RANTES cytokine in endometriosis." (PMID 31435600, 2019). "However, this is not so obvious due to the failed attempts to use anti-TNF-α drugs (like infliximab) in case of endometriosis-related pain due to the lack of clinical effects." (PMID 30518097, 2018). "Moreover, transient inhibition or reduction of miR-223 expression exacerbated endometriosis, as indicated by the histological indices, increased NLRP3, IL-1β, IL-6, and TNF-α secretion, as well as the IL-1β-inducible chemokines CXCL1 and CXCL2 mRNA transcripts." (PMID 30186287, 2018). "Thus, studies on the use of anti-TNF-α have stalled and no new data have emerged to support the use of such compounds for the treatment of symptomatic endometriosis." (PMID 26949527, 2016).
endometriosis (continued). "Therefore, we investigated the concentrations of TNFα and oxidative stress in ovarian follicular fluids to see if they can shed light on the mechanism by which ultralong GnRHa therapy improves the IVF-ET outcome in endometriosis patients." (PMID 25331066, 2014). "Furthermore, endometrial expression of TNF-α mRNA was significantly higher during the menstrual phase in women with endometriosis compared to women without endometriosis." (PMID 23626717, 2013). "In addition, TNF-α, endometrial stromal cell-derived IL-6, and monocyte chemoattractant protein (MCP-1) could stimulate peritoneal macrophages toward M2-polarization and modulate endometriosis." (PMID 40507929, 2025). "However, there are studies that have shown that the serum levels of IL-10, TNF-alpha, and soluble HLA-G (sHLA-G) alone are not sufficient for differentiating between endometriosis and cancer, despite being significantly increased compared to their levels in benign lesions." (PMID 38337827, 2024). "Moreover, the transcriptional activity of many proinflammatory cytokines, such as IL-1, IL-6, IL-8, TNF-α, MIF, and intercellular cell adhesion molecule-1 (ICAM1), is activated by NF-κB signaling, demonstrating the key role of NF-κB in the inflammatory response in endometriosis." (PMID 37108154, 2023). "In this context, the combination of anti-TNFα and anti-IFN should be further investigated to determine whether this combination synergistically suppresses endometriosis progression and relieves endometriosis symptoms without the adverse effects associated with current hormonal therapy." (PMID 36358904, 2022). "Women affected by endometriosis are more likely than those who were not affected by it to have higher levels of proinflammatory cytokines such as interleukin-1 beta (IL-1), interleukin-6 (IL-6), and tumor necrosis factor-α (TNF-α) occurring locally, in the peritoneal cavity, and systemically." (PMID 33693010, 2020). "These include interleukin (IL)-6, tumor necrosis factor-alpha (TNF-α), and sometimes IL-1β and IL-8, which are significantly increased compared to women without endometriosis." (PMID 41590512, 2026). "Although no changes in cell uptake were detected, sEVs from endometriosis induced a polarization of macrophages toward an M2 phenotype, characterized by lower IL1B and TNF expression and a tendency to increase MRC1 and ARG1 levels." (PMID 39062452, 2024). "They measured the TNF-α level and found that the average serum level of TNF-α in patients with endometriosis was higher than in patients without endometriosis." (PMID 37630196, 2023). "We discuss how initial studies of related targets, such as tumor necrosis factor-alpha (TNF-α), failed to result in novel, non-hormonal therapy, and we introduce new players which have gained attention for their role in the pathophysiology of endometriosis." (PMID 26949527, 2016).